RNU6-542P (RNA, U6 small nuclear 542, pseudogene)
Gene: Small nuclear RNA gene on chromosome 2 (74,319,399 to 74,319,501, forward strand). Ensembl gene ENSG00000252214.
Homologues: Orthologues: chimpanzee U6 (99% identical), mouse Gm56091 (61% identical), rabbit U6 (55% identical). Paralogues in human: RNU6-684P (76% identical), RNU6-1024P (74% identical), RNU6-1289P (74% identical), RNU6-1322P (74% identical), RNU6-242P (74% identical), RNU6-310P (74% identical), RNU6-411P (74% identical), RNU6-500P (74% identical), RNU6-834P (74% identical), RNU6-838P (74% identical), RNU6-116P (73% identical), RNU6-1209P (73% identical), and 1282 more.